TNF (tumor necrosis factor)
Diseases named in the same sentence as TNF in open-access papers (continued):
Sharing a sentence is not in itself a finding about the gene and the disease.
melanoma (continued). "Recent studies have revealed that IL7 plays a significant role in glioma, melanoma and leukemia by contributing to anti-tumor effects through the release of cytokines, including IFNG, IL1A, IL1B, TNF, IL2 and IL4." (PMID 37958451, 2023). "The unique combination of TNF-α and IFN-γ induced PANoptosis in different cancer cell types such as colon, melanoma, lung cancer and leukemic cell lines, highlighting the robust cell death induction by TNF-α and IFN-γ in a wide range of cancer cells." (PMID 38077402, 2023). "In melanoma cells, TNFα/TNFR1 signaling mediates the significant upregulation of the pro-inflammatory cytokine IL6 gene supported by the TNF-α overexpression." (PMID 36829966, 2023). "In this study, we observed the presence of MDM2 and SURVIVIN expression in in-transit metastases of melanoma and the correlation between this and the clinical response to ILP with TNF and melphalan." (PMID 38138884, 2023). "Consistent with these in vitro data, CD47 mRNA expression in TCGA melanomas had highly significant positive correlations with MCL1, CD40LG, TIGIT, and TNF mRNA expression." (PMID 36768931, 2023). "The combination of TNF-α, IFN-γ and melphalan in an isolated limb perfusion setting shows impressive remission rates in irresectable soft tissue sarcomas and melanoma and remains a possible treatment option for advanced disease." (PMID 37610672, 2023). "Analysis revealed that XBP1ΔcDC1IRE1trunc-cDC1 mice showed normal B16ChOVA melanoma tumor growth, and normal CD8+/CD4+ T cell tumor infiltration and function compared to control littermates, and a modest decrease in TNF+ CD8+ T cells." (PMID 37346037, 2023). "Based on their strong positive correlations with CD47 mRNA expression in the TCGA melanoma data, we selected MCL1, CD40LG, TNF, and TIGIT to examine their regulation by CD47 signaling in human Jurkat T lymphoblast cells." (PMID 36768931, 2023). "TLR7 agonist imiquimod binding RT-induced ROS accelerates autophagy in melanoma through MAPK and NF-κB signaling pathways and increases CD4 and CD8+T cell ratios through IFN-γ and TNF-α production." (PMID 37600785, 2023). "GILT expression in melanoma cells is induced by interferon-γ (IFN-γ) and tumor necrosis factor-α (TNF-α), and to a lesser extent by interleukin-1β (IL-1β)." (PMID 35565329, 2022). "hsa-miR-498 was enriched in human melanoma exosomes and was shown to regulate TCR signaling and TNFα secretion and contribute to tumor immune escape, indicating that it has the potential to become a therapeutic target." (PMID 35600372, 2022). "The human melanoma cell lines SK-MEL-28 and WM115 were treated with the cytokines IFN-γ and TNF as CIS, the chemotherapeutic agent doxorubicin, and the cell cycle inhibitor palbociclib as TIS." (PMID 35563820, 2022). "We measured the TNF-α and IFN-γ levels in the supernatants of WT and KLK6−/− BMDMs after being co-cultured with B16F10 melanoma cells." (PMID 36552865, 2022). "First of all, we established senescence induction in the human melanoma cell lines SK-MEL-28 and WM115 using the cytokine cocktail IFN-γ and TNF and the drugs doxorubicin and palbociclib." (PMID 35563820, 2022). "Inflammation-related proteins are detected to upregulate in nearly all skin cancers, such as the interleukin family in melanoma, the S100 calcium-binding proteins in SCC, and tumor necrosis factor(TNF) in cutaneous T-cell lymphomas (CTCL)." (PMID 36338621, 2022). "Similarly, daily injection of a CD13-specific VHH single-domain antibody fused to a mutated (Y86F) single-chain murine TNF (50 μg/mouse) could selectively activate the tumor neovasculature in a murine melanoma model without detectable toxicity." (PMID 35890309, 2022). "In the present study, we induced senescence in two human melanoma cell lines, SK-MEL-28 and WM115, with an established cytokine cocktail of IFN-γ and TNF, the chemotherapeutic agent doxorubicin, and the CDK4/6 inhibitor palbociclib." (PMID 35563820, 2022).
melanoma (continued). "We also treated B16BL6 melanoma bearing animals with PLD, alone or in combination with TNF-α, and found a significantly higher drug accumulation and tumor response in animals treated with the combination." (PMID 36297598, 2022). "Interfering Twist1 inhibited epithelial-mesenchymal transition (EMT) and limited lipopolysaccharide-induced inflammation, migration, and invasion in A2058 melanoma cells with the decrease of MMP1/9, VEGF, TNF-α, and IL-6." (PMID 35321317, 2022). "IHC/IF analyses of melanoma lesions identified substantial populations of TGF-β-expressing and TNF-α-expressing CD20+ TIL-B in melanoma lesions, while the presence of IL-10+ TIL-B was less frequent." (PMID 35909944, 2022). "Following our observations of systemic dysregulation among cytokine-expressing B cells in patients with melanoma, we sought to investigate cytokine expression profiles (regulatory IL-10 and TGF-β, and pro-inflammatory TNF-α) within the TIL-B compartment." (PMID 35909944, 2022). "To compare the biological activity of human and mouse Usp27x isoforms during TNF/pIC treatment, we generated 1205Lu and WM1158 melanoma cells inducibly expressing either mUsp27xS or hUsp27xL." (PMID 35044632, 2022). "Nonetheless, a role for CD8+ T cells in the retardation of tumor growth in the lungs is plausible as there is a significant induction of TNFα and IFNγ in lung-infiltrating CD8+ T cells in the melanoma-bearing lungs." (PMID 36733396, 2022). "Similar upregulation of MHC Class I by CDK4/6i was also demonstrated in the murine melanoma cell line B16-OVA with co-culture experiments showing enhanced IFN-γ and TNF-α release when treated with OT-1 T cells." (PMID 34944961, 2021). "Another study using a melanoma mouse model suggested that strain L. reuteri FLRE5K induces higher levels of the cytokines TNF-α and IFN-γ, which stimulate immunity and interfere with proliferation of melanoma cells." (PMID 34960243, 2021). "Activation of the RIPK1-dependent cell death program in target cells by T cell–derived TNF accelerates murine cardiac allograft rejection and synergizes with anti-PD1 administration to destroy checkpoint blockade–resistant murine melanoma." (PMID 34752416, 2021). "Our results highlight the role of TAMs in biologically aggressive primary melanomas, suggesting that prometastatic TAMs are characterized by higher secretion of CCL20/TNF/VEGFA cytokines." (PMID 34439098, 2021). "Using the mouse melanoma cell line B16F10.9, which are usually resistant to TNF-α-mediated cell death, apoptosis was enhanced in the presence of IL6/sIL6R." (PMID 34411141, 2021). "The melanoma inhibitor of apoptosis protein (ML-IAP) is an important regulator of apoptosis that inhibits caspase activation and TNF signaling, frequently overexpressed in melanoma cells, but with low expression in normal melanocytes." (PMID 34944611, 2021). "CD40 expression on melanoma cells stimulates the formation of CD8 T cell cytokines including IL-13, IL-6, TNF-α, and granulocyte/macrophage colony-stimulating factor (GM-CSF) and impedes brain metastasis which is common among melanoma patients." (PMID 32902664, 2021). "We show that TNFα is a poor inducer of antigen presentation molecules HLA-ABC and HLA-DR but readily induces the PD-L2 immune checkpoint in melanoma cells." (PMID 34073253, 2021). "Cancer cells release large amounts of cytokines including TNF-α, IL-6, IL-12, VEGF, and TNFR2, which enhances MMP-2 enzymatic activity and leads to increased invasiveness of melanoma." (PMID 34068679, 2021). "Since TNF-α is a well-established inhibitor of tumor growth in a variety of cancers, we wondered if the ILC2-derived TNF-α had any direct effect on B16 melanoma cells." (PMID 34531874, 2021).
melanoma (continued). "From these analyses, higher concentrations of VEGF-A, PDGF-BB, IL-1RA, PIGF-1, IFN-γ, TNF-α, MIP-1α, and SCF were observed in melanoma patients." (PMID 33574842, 2021). "A phase II trial incorporating anti-EDB IL-2 and TNF immunocytokines in 20 stage III and IV melanoma patients resulted in 30% of lesions experiencing a complete response." (PMID 33803078, 2021). "In epithelial cells and melanoma cells, TGF-β induces apoptosis while TNF-α is anti-apoptotic, and in splenocytes and osteoblasts, TGF-β is anti-apoptotic while TNF-α induces apoptosis." (PMID 35069596, 2021). "Along these lines, mitogenic and pro-inflammatory signals coming from hepatocyte growth factor (HGF) and tumor necrosis factor-alpha (TNFα), respectively, upregulate CD73 expression in melanoma cell lines that were unmethylated." (PMID 33430239, 2021). "In contrast, ML NK cells from the same HD had significantly increased IFNγ, TNF, and CD107a expression after restimulation with DM6 and M14 melanoma cells." (PMID 34187852, 2021). "miR-134 acts as an immune escape facilitator in melanoma cells, not only directly targeting B7-2 to reduce its expression, but also mediating the reduction of interferon-γ (IFN-γ) and tumor necrosis factor-α (TNF-α) levels produced by lymphocytes." (PMID 35116035, 2021). "First, we established conditions to quantify by multicolor fluorescent-microscopy the content of CCL20, TNF, and VEGFA in CD68+ cells in FFPE melanoma tissues." (PMID 34439098, 2021). "In this study, melanoma patients showed higher levels of VEGF-A, PDGF-BB, IL-1RA, PIGF-1, IFN-γ, TNF-α, MIP-1α, and SCF, but decreased levels of BDNF, SDF-1α, MCP-1, Eotaxin, EGF, and IL-7 than those in healthy patients." (PMID 33574842, 2021). "We previously identified co-expression of CCL20, TNF, and VEGFA cytokines by tissue TAMs in an exploratory set of 7 metastasizing melanomas." (PMID 34439098, 2021). "Under the TNFα overexpression, the mRNA of two important genes was significantly upregulated: pro-inflammatory cytokine IL6 in melanoma cells A375hTNFa, and pro-apoptotic ligand TRAIL in carcinoma cells HT29hTNFa." (PMID 33957885, 2021). "Compared to the control group, melanoma patients had higher levels of VEGF-A, PDGF-BB, IL-1RA, PIGF-1, IFN-γ, TNF-α, MIP-1α, and SCF, but lower levels of BDNF, SDF-1α, MCP-1, Eotaxin, EGF, and IL-7." (PMID 33574842, 2021). "IL-6, TNF-α, and IFN-γ expression in melanoma cells are also suppressed by axitinib, a selective inhibitor of VEGFRs and PDGFRs." (PMID 34122447, 2021). "TNF-α upregulates COX-2 expression in melanoma cells, which is decreased in melanoma cells co-cultured with EPA or DHA, subsequently decreasing tumor invasion." (PMID 34829495, 2021). "Proinflammatory cytokines, such as interferon-gamma (IFNγ) and tumor necrosis factor-alpha (TNFα), and epigenetic modulators, such as histone deacetylase (HDAC) inhibitors, can induce CD40 expression on melanoma cells." (PMID 34092233, 2021). "Under the TNFα overexpression, significant upregulation of two genes was observed: proinflammatory cytokine IL6 gene in melanoma cells A375 and gene for pro-apoptotic ligand TRAIL in colorectal carcinoma cells HT29, both mediated by TNFα/TNFR1 signaling." (PMID 33957885, 2021). "TNFα effects were reversible in both melanocytic (SKMel28, MP46, MEL270, OMM1) and dedifferentiated (HT144, MM200) melanoma cell lines, with the partial to complete restoration of MITF and Melan A expression after TNFα removal." (PMID 34073253, 2021). "Melanoma cells express CTLA-4, and the engagement of CTLA-4 on primary melanoma cell lines induced ADCC and TNFα production by NK cells." (PMID 33810032, 2021). "Using monocyte-derived macrophages, with either GM-CSF or with M-CSF, which are known to prime towards M1 or M2 phenotypes, we produced in vitro melanoma-conditioned macrophages expressing CCL20 and TNF (M1-primed) or VEGFA (M2-primed)." (PMID 34439098, 2021).
melanoma (continued). "TNF‐α not only compromised CD8+ tumor‐infiltrating lymphocytes, but also reduced the degree of PD‐L1 expression on tumor cells in a murine model of melanoma." (PMID 33300678, 2021). "Multiple trials of cancer treatment based on TNF and its derivatives (L19TNF, CNGRC peptide-TNF conjugate (NGR-TNF)) were carried out for melanoma and other solid tumors." (PMID 33917839, 2021). "We obtained with our protocol numerous pure M1-CTLs which were producing high amounts of IFNγ, TNFα and IL-2, and were able to specifically lyse both MART-1-pulsed T2 cells and melanoma-derived cell lines very efficiently, with a high functional avidity." (PMID 34566953, 2021). "TNF and TNFR have been detected in sEVs of melanoma cells and were able to transmit redox signaling to adjacent cells, leading to tumor immune escape." (PMID 33508878, 2021). "Similar enrichments were observed for experimental gene sets of IL-1β-, TNFα-, or TGF-β1-response induced in human melanoma cell lines, primary endothelial cells, fibroblasts, melanocytes, or CD4+ T cell clones." (PMID 32917858, 2020). "These melanoma-derived exosomes were enriched with miR-181a/b and miR-498, which directly bound to the 3′UTR of TNF and decreased TNFα secretion in CD8 T cells." (PMID 32722019, 2020). "Similar results were obtained also by another study showing that the development of B16 murine melanoma was accelerated when the melanoma cells were co-injected with MSCs pre-incubated with IFN-γ and TNF-α compared with controls." (PMID 32637408, 2020). "The cytokines IFN-γ and TNF-α and the expression of CD69 were evaluated after OTI TCR CD8+ T cells were incubated with OVA+-B16F10 melanoma cells." (PMID 33597944, 2020). "In melanoma, neutrophils recruited by Toll-like receptor 4 (TLR4) signal can induce cancer cells to migrate to endothelial cells through tumor necrosis factor (TNF), resulting in enhancing cancer metastasis." (PMID 33488618, 2020). "Tumor vasculature‐targeted TNF immunocytokines are being developed, most notably NGR‐TNF and L19‐TNF, which are currently in phase II/III clinical trials for, respectively, mesothelioma and melanoma." (PMID 31912630, 2020). "It has also been shown that MEK and BRAF inhibitors can increase the number of macrophages, as well as their expression of tumor necrosis factor-α (TNF-α), mediating upregulation of MITF expression in melanoma cells through NF-κB activation." (PMID 33291749, 2020). "Hundreds of factors can be secreted by adipocytes, and we focused on TNF-α and IL-6, which have been reported to regulate PD-L1 on kinds of cancer cells but HCC or melanoma." (PMID 32477009, 2020). "Overexpression of IGSF4 lacking the extracellular (IG4ΔEXT) domain potentiates the OTI CD8+ T cells to release IFN-γ and TNF-α and to kill OVA+-B16F10 melanoma cells." (PMID 33597944, 2020). "In the immunotherapy using anti-CTLA-4 or IL-2 in mice, the production of tumor necrosis factor-a (TNF-a) in tumor cells and the accumulation of T cells led to an increase in EZH2 expression in melanoma cells." (PMID 32859239, 2020). "We previously showed that the host deletion of ADAM9 leads to enhanced growth of grafted B16F1 melanoma cells by a mechanism mediated by TIMP1 and the TNF-α/sTNFR1 pathway." (PMID 32906814, 2020). "Concurrently, the expression of IFN-γ and TNF-α, major cytotoxic effector cytokines, in CD4+ and CD8+ T cells was higher in B16 melanoma of Lsp1 KO mice than in control mice." (PMID 33020243, 2020). "In in vivo melanoma models, MAPK-targeted agents induce tumor necrosis factor α (TNFα) production by macrophages, which promotes NFkB pathway activation and higher MITF expression." (PMID 33036192, 2020). "Since tumor‐bearing mice tend to be sensitized toward TNF toxicity, we next tested mCD13‐AFR in the B16Bl6 melanoma model." (PMID 31912630, 2020). "TNF-α has been shown to enhance the expression of PD-L1 on CD8+ T cells in cancer, including melanoma." (PMID 32310956, 2020).
melanoma (continued). "For example, exosomes derived from melanoma are capable of inducing expression of pro-angiogenic and inflammatory genes including hypoxia-inducible factor 1 alpha (HIF-1α) and TNF-α in lymph nodes." (PMID 33291683, 2020). "Therefore, to figure out whether A20 was involved in the regulation of cell death, we adopted positive controls of melanoma cell apoptosis, necroptosis, and pyroptosis induced by TS (TNF-α and SM-164), TSZ (TNF-α, SM-164 and Z-VAD-FMK), and FC (FeSO4 and CCCP) respectively." (PMID 32968045, 2020). "We also evaluated the impact of proinflammatory molecules TNFα and IFNγ on IL32 expression and dedifferentiation in melanoma cell lines in vitro." (PMID 30953519, 2019). "Our study showed that TNF-α promoted the expression of MMP-9 and Madcam1 in melanoma cells, which contributed to melanoma growth and metastasis." (PMID 31600735, 2019). "In agreement with this concept, we have shown that TNF blockers improve the anti-tumor therapeutic activity of ICB in mice and based on these findings we are currently evaluating the combination in melanoma patients enrolled in the TICIMEL clinical trial." (PMID 31727152, 2019). "TNF, IFN and IL-2 have been used to treat a variety of a human solid tumours, including melanoma, renal cell carcinoma, multiple myeloma and ovarian cancer." (PMID 30987001, 2019). "Their therapeutic options are further limited because BRAF-wild-type melanomas frequently display treatment resistance due to activated MEK1 (MAP2K1), PKCα, PDGFR-β, AKT, or TNFα pathways." (PMID 31615091, 2019). "On the contrary, c-Jun exhibited an extended half-life in melanoma cells harboring the inactive CS-ITCH mutant, while becoming less stable in cells stimulated with TNFα." (PMID 31015455, 2019). "We selected these three melanoma cell lines to observe the parallel impact of TNFα and IFNγ on IL32 and the melanoma differentiation state because they exhibited a low AXL/high MITF differentiated genetic signature." (PMID 30953519, 2019). "We found that TNFα and IFNγ, which promote a dedifferentiated melanoma phenotype, also induce IL32 expression in non-IL32 expressing melanoma cell lines by impacting activity at the promoter level." (PMID 30953519, 2019). "Similar inhibitory effects on TNF-α production exerted by α-MSH were observed in human monocyte/macrophages, melanocyte and melanoma cells, and human keratinocytes." (PMID 31649620, 2019). "The authors notably based their rationale for such a combination on observations we made, supporting the use of TNF blocking agents to promote the efficacy of ICB in cancer and especially melanoma." (PMID 31727152, 2019). "Consistently, a kinase activity assay in melanoma cells (A375), using GST-IκB-α as substrate and TNF-α as stimulus, indicated a reduced phosphorylation of GST-IκB-α in FKBP51 knockdown cells compared with the corresponding controls." (PMID 30669684, 2019). "We have previously shown that autocrine TNFα is an important element that promotes RIP1 expression and NF-κB activation in melanoma cells." (PMID 29880840, 2018). "IPA analyses of transcriptomic expression profiles indicated TNF, the MMP-2 and IL-6 pathways as the most significantly upstream regulators, strongly suggesting them as possible key modulators of the melanoma cell aggressiveness." (PMID 30591049, 2018). "In melanoma cell lines, VDR mediates the repression of TNF-α-induced IL-8 promoter activity by calcitriol." (PMID 29865262, 2018). "In contrast, zymosan significantly induced TNF-α and TLR-2 mRNA expression in both healthy (Z) animals and in melanoma-bearing (ZM) animals." (PMID 29588627, 2018). "Only melanoma-infiltrating, tumor-specific T lymphocytes (TILs) upregulated PD-1, LAG-3, and TIM-3 and showed reduced TNF-α, IFN-γ, and IL-2 secretion ability when compared with virus-specific cells." (PMID 30108594, 2018).